CXCR2 (C-X-C motif chemokine receptor 2)
Diseases named in the same sentence as CXCR2 in open-access papers (continued):
Sharing a sentence is not in itself a finding about the gene and the disease.
tumor (continued). "Tumor-induced NETosis is mainly triggered by CXCR1 and CXCR2 ligands, which could be constrained by CXCR1 and CXCR2 inhibitors." (PMID 34868992, 2021). "Tumor size was measured at E10 egg inoculated with A2780 or ACRP, NC and CXCR2 KD." (PMID 34038868, 2021). "Furthermore, we identified potential molecular targets based on our expression data in NE-low and immune-oasis tumor subsets, including CD70, ANXA1, ITGB6, TP63, IFI27, YBX3 and CXCR2." (PMID 34200100, 2021). "A recent finding demonstrated that SHP2 inhibition in tumor cells increases the expression of CXCR2 ligands, which suppresses M2 macrophages and promotes gMDSC infiltration, suggesting combined inhibition of SHP2 and CXCR2 in lung cancer." (PMID 34728626, 2021). "Therefore, co-localization of T cells and tumor cells were able to be detected by living imaging, and effects of CXCR-1 and CXCR-2 on T cell trafficking were observed directly." (PMID 33777013, 2021). "As AKT and STAT3 pathways were proven to be important for PC tumorigenesis, it would be reasonable to propose that CXCL5/CXCR2 signaling might activate AKT and STAT3 signaling pathways to promote tumor progression in PC." (PMID 33458757, 2021). "Interestingly heterozygous animals (PyMT−Cxcr2−/+) also exhibit tumor sizes in between the ones of PYMT WT and PyMT−Cxcr2−/− mice, showing that Cxcr2 expression level follows a gene–dose effect." (PMID 34070438, 2021). "In multivariate analysis, tumor size, nodal involvement, ductal histology, lack of adjuvant chemotherapy and low densities of TILs or of CXCR2+ cells were independent poor prognostic factors of OS." (PMID 34066060, 2021). "Also, CXCL5 promotes tumor angiogenesis, and new blood vessels act as tumor metastasis channels; CXCL5/CXCR2 can release matrix metalloproteinase-9 (MMP-9), destroys endothelial cells and matrix barrier, and promotes tumor metastasis." (PMID 33869023, 2021). "Furthermore, they mediate tumor angiogenesis and CXCR2 has been shown to be a driving force on the vascular mimicry (VM) formation in GBM patients, indicating a key role of this signaling pathway in the tumor blood supply." (PMID 34681839, 2021). "Waugh and Wilson reported IL-8 secreted by tumor cells plays an important role in the tumor microenvironment and observed that the expressions of the IL-8 receptors, CXCR1 and CXCR2, were elevated in cancer cells, endothelial cells, and tumor-infiltrating neutrophils and macrophages." (PMID 34267603, 2021). "Another important role of CXCR2 is to regulate neutrophils migration to tumor microenvironment, and neutrophils lacking CXCR2 are preferentially retained in bone marrow." (PMID 33814009, 2021). "The CXCL5/CXCR2 axis could activate multiple downstream signaling pathways, including PI3K/AKT, ERK1/2, and STAT3 to promote tumor progression in cancers." (PMID 33458757, 2021). "Moreover, combining a CSF1R inhibitor with a CXCR2 inhibitor was shown to block granulocyte infiltration of tumors triggered by the inhibition of CSF1R and significantly reduce tumor growth." (PMID 34124076, 2021). "Although lean CXCR2 cKO mice had a decreasing trend in body weight with an advanced tumor burden (from 9 weeks after OC cell injection), this was not significant." (PMID 34638514, 2021). "Several preclinical studies have demonstrated that CAR T cells expressing chemokine receptors, including C-X-C motif chemokine receptor 1 (CXCR1), CXCR2, CCR2, CCR4, and C-C chemokine receptor type 2 (CCR2b), showed enhanced trafficking to tumor lesions and superior antitumor efficacy." (PMID 34209505, 2021). "The tumor tissues in HFD-fed CXCR2 cKO mice had lower inflammatory areas and PCNA and F4/80 expressions, compared to those in HFD-fed WT mice, indicating a reduced tumor burden." (PMID 34638514, 2021). "On the contrary, CXCR2 WT mice seemed to have a higher tumor burden rather than an ascites burden from OC under obese conditions." (PMID 34638514, 2021).
tumor (continued). "In fact, inhibition of CXCR2 and CCR2 could reverse tumor progression promoted by type I collagen deletion in myCAFs as was evident in a PDAC mouse model potentially by cytotoxic T cell trafficking." (PMID 34646829, 2021). "Moreover, OS of tumor-bearing mice was significantly improved under therapy with CAR T CXCR1 and CXCR2." (PMID 34203660, 2021). "Also, T cells engineered to express CXCR2 or CXCR1 have greater capacity for homing and infiltration of tumor in murine models." (PMID 34454518, 2021). "Murine MDSCs might also express disparate combinations of chemokine receptors, notably CX3CR1, CXCR2, CXCR4, and/or CCR2, which are critical for migration of MDSCs from the bone marrow and/or recruitment to tumor niche or sites of infectious disease." (PMID 34525267, 2021). "CXCR2 binds chemokines containing the glutamic acid-leucine-arginine (ELR) motif such as CXCL5 and CXCL8 that are involved in angiogenesis and also promote tumor progression." (PMID 34831316, 2021). "We confirmed in this large cohort of samples what we had observed during the IHC optimization process: scattered CXCR2-positive cells were restricted to the tumor stromal compartment and tumor cells were never immune-reactive." (PMID 32727083, 2020). "Furthermore, ACKR1 protein expression was localized on normal brain and tumor microvascular cells, while CXCR1 and CXCR2 were present on tumor infiltrating leukocytes." (PMID 32456359, 2020). "In contrast, granulocytic MDSCs (G-MDSCs) expressed high levels of the MIF non-cognate receptor CXCR2 and showed minimal accumulation in the tumor microenvironment." (PMID 32625208, 2020). "TANs are recruited in the tumor environment mainly via the chemokine (CK) receptors CXCR1 and CXCR2, although many other CKs and coupled receptors could be involved." (PMID 31991796, 2020). "Treatment of lean animals with combinatorial AdT+CpG+CXCR2 antagonist (CXCR2a) provided no benefit over that of AdT+CpG alone with regard to tumor burden or MDSC accumulation." (PMID 33123173, 2020). "During the formation of the tumor metastasis microenvironment, increased secretion of CXCL1 and CXCL2 by endothelial cells and megakaryocytes promotes the release of neutrophils into circulation via the regulation of CXCR2 signaling." (PMID 33363026, 2020). "These selected Ab and ISH were all showing CXCR2-positive cells only in the stromal compartment or within vessels but never on tumor cells." (PMID 32727083, 2020). "Interestingly, these pathways are utilized by a series of chemokines and their receptors, such as CCL20/CCR6, CCL25/CCR9, CXCL1/CXCR2, CXCL8/CXCR1-2, CXCL12/CXCR4, and CX3CL1/CX3CR1, to inhibit apoptosis and promote tumor cell growth and proliferation." (PMID 31991604, 2020). "A previous small study has shown that another CXCR2 Ab (no more commercially available) stained tumor cells in a series of only 37 patients, in which no validation of the Ab used was presented." (PMID 32727083, 2020). "Given that several αvβ6-positive tumor cell lines were found to secrete IL-8 both in vitro and when grown as xenografts in vivo, we engineered A20-28z CAR T-cells to co-express the IL-8-specific chemokine receptors, CXCR1, or CXCR2." (PMID 31091832, 2019). "The results suggested that overexpression of CXCL6 contributed to tumor growth and pulmonary metastasis via activating PI3K/AKT and Wnt/β-catenin pathways, which could be repressed by treatment with CXCR2 antagonist SB225002." (PMID 30984000, 2019). "The observed number of Ki-67-positive proliferating cells was similar in the tumor/juxtatumoral stroma and desmoplastic stroma, also indicating that heterozygous knockout of Cxcr2 in vivo was not directly correlated to proliferation of PDAC." (PMID 30659170, 2019). "Finally, overexpression of CXCL6 significantly contributed to tumor growth, pulmonary metastasis and activation of PI3K/AKT and β-catenin pathways in nude mice in vivo, which were repressed by treatment with CXCR2 antagonist." (PMID 30984000, 2019).
tumor (continued). "Finally, in a prostate cancer model, CXCR2 inhibition by SB265610, decreased recruitment of myeloid cells and enhanced Docetaxel-induced senescence, limiting tumor growth." (PMID 30894861, 2019). "The identification of the specific signaling pathway activated by CXCR2 provides a novel regulatory mechanism of STAT3 activation in myeloid cell differentiation and a potential strategy for reducing immune suppression in the tumor microenvironment." (PMID 31395859, 2019). "Likewise, human neutrophils, after CXCR2-dependent recruitment, and MAPK activation have the ability to induce multiple tumor promoting mechanisms, which includes the cortactin-mediated induction of tumor cell invasion and metastasis in patients." (PMID 31293583, 2019). "So, in this study, SB225002, as a CXCR2 antagonist, may also block the effect of CXCL6, CXCL8 on the communication between OS cells and tumor microenvironment, which needs to be evaluated in our future research." (PMID 30984000, 2019). "Co-expression of the matched chemokine receptor CXCR2 in 2nd generation CAR T-cells targeted to the integrin αvβ6 results in increased migration in response to recombinant hIL-8 and to tumor-cell derived supernatant in an IL-8-mediated manner, without affecting cytotoxic function." (PMID 31091832, 2019). "Thus, the CXCLs–CXCR2 axis is highly involved in PDAC progression, especially in tumor–stromal interactions and the tumor microenvironment." (PMID 30659170, 2019). "Given that arginase 2 mRNA was expressed in the healthy tissue and not specifically elevated in the tumor both in our mice and patient tumors, we focused on characterizing arginase 1 expression in CD66b or CXCR2 expressing myeloid cells in the patient tissues." (PMID 30728077, 2019). "Of note, since that CXCR-2 is also expressed by myeloid-derived immunosuppressive cells in PDAC, its inhibitor may exert anti-tumor efficacy through multiple mechanisms of action." (PMID 31417869, 2019). "Tumours were reduced when tumour-bearing mice were treated with both the CSF1R inhibitor and a C–X–C Motif Chemokine Receptor 2 (CXCR2) antagonist (to prevent PMN-MDSC migration), and tumours were completely blocked when a PD-1 antibody was added to this combination." (PMID 31289350, 2019). "The animals that were treated with sarcosine treated DCs had significantly slowed tumor growth over time compared to animals receiving non-sarcosine treated DCs and sarcosine treated DCs treated with CXCR2 neutralizing antibody." (PMID 31753028, 2019). "Taken together, these results indicate that the lack of CXCR2 on GMPs reduces the generation of MDPs, which are the hematopoietic progenitor cells of mo-MDSCs under tumor conditions." (PMID 31395859, 2019). "Extremely low frequencies of NK cells (<0.5%) were found within PDAC tumors, which was attributable not to the low expression of tumor chemokines, but to the lack of chemokine receptor, CXCR2." (PMID 31024520, 2019). "No killing of αvβ6-negative CAL51 or Panc1 tumor cells was observed upon co-culture with A20-28z, A20-28z or A20-28z CXCR2 CAR T-cells." (PMID 31091832, 2019). "Even in PKF mice with Cxcr2-wild type, only a few CD8+ T cells were observed in the tumor lesions." (PMID 30659170, 2019). "Moreover, the CXCR1/CXCR2 antagonist inhibited CRC liver metastasis by decreasing tumor angiogenesis and facilitating tumor cell apoptosis in a mouse model." (PMID 30691207, 2019). "After one week, tumor-bearing mice were treated without or with CXCR2 inhibitor SB225002 for another 3 weeks." (PMID 31390756, 2019). "Furthermore, as the tumor cells secrete TGFβ, deletion of TGFβ receptor 2 (Tgfbr2) within the tumor is demonstrated to increase CXCL1/CXCL5 –CXCR2 chemokine and chemokine receptor signaling." (PMID 29966014, 2018). "Furthermore, CXCL8 secreted by tumor and Treg cells has been shown to sustain MDSC migration and degranulation via CXCR1 and CXCR2 signalling to support cancer dissemination." (PMID 30591657, 2018).
tumor (continued). "CXCR2 expression was significantly correlated with tumour differentiation but not RCC stage (data not shown)." (PMID 30246456, 2018). "Although a bunch of CXCR2 antagonists have been identified, the anti-tumour metastasis effect of CXCR2 antagonists has not been considered in most cases." (PMID 30109074, 2018). "CXCR1 was expressed equally in all carcinomas, as opposed to CXCR2 and 4, which were only expressed in few tumours." (PMID 29976164, 2018). "Both CXCR1 and CXCR2 were required for both spontaneous and induced lung colonization by these cells, but not for s.c. tumor growth (and EV2J and K)." (PMID 28341702, 2017). "The expressions of CXCL1 and its receptor CXCR2 were significantly increased following radiation in tumor cells, which may create a constitutively activated CXCL1/CXCR2 signaling." (PMID 28518141, 2017). "Finally, we defined a tumor-derived TGF-β-triggered CXCL1/2/5- and CXCR2-dependent recruitment of MDSC into the liver." (PMID 28243237, 2017). "At the same time, the Ma S group found that the CXCL5 production of tumor cells could be induced by IL-17A, and the infiltration of MDSCs in tumor sites was mediated by CXCL5/CXCR2." (PMID 28002798, 2017). "At a ∼250mm3 tumor volume, mice were divided into 4 groups intraperitoneally injected with: vehicle, Anakinra (human grade IL-1β antagonist; IL-1ra, 10mg/kg), SB265610 (CXCR2 inhibitor, 2mg/kg) or both (same concentrations) for 4 consecutive days." (PMID 29262555, 2017). "4T1 cells were co-cultured with or without CXCR2+ MDSCs sorted from spleen of 4T1-tumor bearing mice, in vitro proliferation was supervised by Real-Time Cell Analyzing (RTCA, AceaBio, China) method." (PMID 29383101, 2017). "We show that these cells infiltrate and possibly predispose the local microenvironment for the successful settling of disseminated NRAS‐mutant tumor cells, and include CD45+CD11b+Ly6c+ and CD45+CD11b+Ly6g+ hematopoietic as well as CXCR2+CD34+ endothelial progenitors." (PMID 28341702, 2017). "Compared to mice without tumor metastatic, the percentage of CXCR2+ MDSCs in the peripheral blood was higher in mice with lymph node metastasis (76.7 ± 6.0% vs 58.1 ± 2.8%)." (PMID 29383101, 2017). "The initially secreted chemokines at the tumor site play a key role defining the composition of the tissue stroma and recruiting tumor infiltrating leukocytes bearing specific chemokine receptors (CXCR1, CXCR2, CCR2, CCR4, or CCR5, among others)." (PMID 25688243, 2015). "To investigate whether CXCL1 is the central angiogenesis and tumour-promoting factor in our model and a potential therapeutic target, we treated the mice with SB225002, a small-molecule antagonist of CXCR2." (PMID 25734337, 2015). "CXCR2 is expressed on most of circulating G-MDSCs but not on M-MDSCs and is prerequisite for G-MDSCs to be recruited to tumor microenvironment." (PMID 26078490, 2015). "CXCR2 was proposed to be involved in the tumour malignancy via EGFR-dependent mechanism 46, while CXCL8 might play a potential role in tumour development by EGFR transactivation." (PMID 24268047, 2014). "MSCs may be recruited into the tumor through FPR2, CCR2, CXCR1, CXCR2, CXCR4, CXCR6, and CX3CR1 depending on the types and locations." (PMID 25110692, 2014). "The co-existence of OIS markers and CXCR2 is strengthened by the analysis of a PDTC sample (#13), representing a model of in situ tumour progression: it displays areas with papillary and solid pattern of growth, previously shown, positive and negative for the expression of senescence markers." (PMID 25268744, 2014). "In addition, CCR6/CCL20 interaction in endometrial adenocarcinoma, CXCR1/2/CXCL7 interaction in clear cell renal cell carcinoma, CXCR2/CXCL8 interaction in nasopharyngeal carcinoma, and CXCR6/CXCR16 interaction in HCC are reported to promote tumor cell growth." (PMID 25110692, 2014). "In the remaining 5 PTMC samples, focal CXCR2 positivity was also observed in tumour areas that were negative for p16INK4a staining." (PMID 25268744, 2014).
tumor (continued). "Further, the secretion of IL-8 from cancer cells may have a variety of effects on the tumor microenvironment, because the IL-8 receptors CXCR1 and CXCR2 are expressed on cancer cells, endothelial cells, neutrophils and tumor-associated macrophages." (PMID 25694811, 2014). "CXCR2 expression in endothelial cells is activated by ELR+CXC chemokines and promotes tumor growth." (PMID 25011526, 2014). "CXCR2 inhibition with SBZ effectively suppressed the expression of Ki-67 in tumor tissues compared to both NTHi exposed and non-exposed control groups." (PMID 24321240, 2013). "Besides tumor cells, IL-8 and its receptors CXCR1 and CXCR2 have been observed on endothelial cells and have been shown to play a role in endothelial cell proliferation." (PMID 22507529, 2012). "The CXCL1 and its receptor CXCR2 are also widely reported to be elevated in CRC, the presence of which may facilitate CRC tumour progression." (PMID 21285972, 2011). "Interestingly, CXCR1 or CXCR2 overexpression in SBC-2 cells induced tumourigenicity, and A375P cells significantly enhanced tumour growth as examined in vivo." (PMID 19401689, 2009). "Therapeutic strategies aimed at modulating N1/N2 balance are advancing, with CXCR2 inhibitors, TGF-β pathway blockade, neutrophil elastase inhibition, and immune checkpoint combinations demonstrating meaningful reductions in N2 infiltration and enhanced tumor control in preclinical models." (PMID 41497164, 2026). "Furthermore, survival analysis revealed that patients with CXCR2-positive tumors (≥ 5% of tumor cells) had significantly shorter overall survival compared with those with CXCR2-negative tumors." (PMID 41486114, 2026). "Specifically, PKM2-induced CXCL1 and MIF produced by tumor cells can bind to CXCR2 and CXCR4 receptors on MDSCs, thereby activating the signaling pathway of MDSCs and triggering cytoskeletal rearrangement, which makes MDSCs chemotactic to the periphery of tumor cells." (PMID 40948745, 2025). "Moreover, TNBC tumor cells secrete granulocyte-macrophage colony-stimulating factor (GM-CSF), TGF-β, and CXCR2 which stimulates TANs to release tumor suppressor M, promotes angiogenesis, and improves tumor cell infiltration or recruitment of neutrophils in TNBC." (PMID 40141437, 2025). "DLBCL-derived IL-8 interacted with its receptor (CXCR2) on neutrophils, resulting in the formation of NETs, which directly increased the expression of Toll-like receptor 9 (TLR9) pathways in DLBCL and subsequently activated the NFκB, STAT3 and p38 pathways, promoting tumor progression." (PMID 41019086, 2025). "Studies have shown that MIF interacts with CD74 or CXCR2 and CXCR4 receptors, activating signaling pathways such as protein kinase B (AKT), extracellular signal-regulated kinases (ERK), and nuclear factor kappa-B (NF-κB), thereby promoting tumor proliferation, angiogenesis, and metastasis." (PMID 41562084, 2025). "This may be due to the absence of the chemokine receptor CXCR2 on patients’ NK cells, resulting in reduced trafficking of the cells into the tumor." (PMID 38322253, 2024). "Notably, peri-tumor but not tumor neutrophil recruitment was CXCR2-dependent suggesting that several distinct pathways govern neutrophil recruitment to the TME." (PMID 39439807, 2024). "MDSCs express several chemokine receptors such as CCR2, CXCR2, CXCR4, and CXCR5, while liver tumor cells or malignant hepatocytes express chemokines such as CCL2, CCL5, CXCL1, CXCL5, and CXCL12, and the chemokine/its receptor axis mediates MDSC infiltration in the tumor microenvironment." (PMID 38397901, 2024).